KNL1 (kinetochore scaffold 1)
Description:
Acts as a component of the outer kinetochore KNL1 complex that serves as a docking point for spindle assembly checkpoint components and mediates microtubule-kinetochore interactions. Kinetochores, consisting of a centromere-associated inner segment and a microtubule-contacting outer segment, play a crucial role in chromosome segregation by mediating the physical connection between centromeric DNA and spindle microtubules. The outer kinetochore is made up of the ten-subunit KMN network, comprising the MIS12, NDC80 and KNL1 complexes, and auxiliary microtubule-associated components; together they connect the outer kinetochore with the inner kinetochore, bind microtubules, and mediate interactions with mitotic checkpoint proteins that delay anaphase until chromosomes are bioriented on the spindle. Required for kinetochore binding by a distinct subset of kMAPs (kinetochore-bound microtubule-associated proteins) and motors. Acts in coordination with CENPK to recruit the NDC80 complex to the outer kinetochore. Can bind either to microtubules or to the protein phosphatase 1 (PP1) catalytic subunits PPP1CA and PPP1CC (via overlapping binding sites), it has higher affinity for PP1. Recruits MAD2L1 to the kinetochore and also directly links BUB1 and BUB1B to the kinetochore. In addition to orienting mitotic chromosomes, it is also essential for alignment of homologous chromosomes during meiotic metaphase I (By similarity). In meiosis I, required to activate the spindle assembly checkpoint at unattached kinetochores to correct erroneous kinetochore-microtubule attachments (By similarity).
Synonyms: AF15q14; CT29; CASC5; KIAA1570; D40; hKNL-1; hSpc105; PPP1R55; Spc7; MCPH4
Tractability: PROTAC: ubiquitination databases record sites on it.
Gene: Protein-coding gene on chromosome 15 (40,594,020 to 40,664,342, forward strand). Ensembl gene ENSG00000137812.
Subcellular location: Nucleus; Chromosome, centromere, kinetochore; Cytoplasm
Subcellular location (Human Protein Atlas): Nucleoplasm; Nuclear bodies
Pathways (Reactome):
Cell Cycle: Amplification of signal from unattached kinetochores via a MAD2 inhibitory signal; Deposition of new CENPA-containing nucleosomes at the centromere; EML4 and NUDC in mitotic spindle formation; Mitotic Prometaphase; Resolution of Sister Chromatid Cohesion; Separation of Sister Chromatids
Signal Transduction: RHO GTPases Activate Formins
Gene Ontology:
Molecular function: microtubule binding; protein binding
Biological process: attachment of spindle microtubules to kinetochore; mitotic sister chromatid segregation; protein localization to kinetochore; regulation of mitotic cell cycle spindle assembly checkpoint; acrosome assembly; attachment of meiotic spindle microtubules to kinetochore; cell division
Cellular component: acrosomal vesicle; kinetochore; Knl1/Spc105 complex; nuclear body; nucleoplasm; nucleus; outer kinetochore; cytoplasm; cytosol
Genetic constraint (gnomAD): Loss-of-function variants: 33 observed, 120.58 expected, observed/expected ratio (o/e) 0.27, 90% interval 0.21 to 0.37. The upper end of that interval is the gene's LOEUF score, 0.37, which puts it in group 1 of 6, group 1 being the genes least tolerant of losing a copy. Missense variants: 2,277 observed, 2,212.7 expected, observed/expected ratio (o/e) 1.03, 90% interval 0.99 to 1.07. Synonymous variants: 712 observed, 749.02 expected, observed/expected ratio (o/e) 0.95, 90% interval 0.89 to 1.01.
Cancer hallmarks: genome instability and mutations (suppresses); escaping programmed cell death (promotes)
Homologues: Orthologues: chimpanzee KNL1 (98% identical), macaque KNL1 (92% identical), rabbit KNL1 (71% identical), dog KNL1 (66% identical), guinea pig KNL1 (62% identical), rat Knl1 (58% identical), mouse Knl1 (57% identical), tropical clawed frog knl1 (28% identical), zebrafish knl1 (14% identical).